LCN2 (lipocalin 2)
Diseases named in the same sentence as LCN2 in open-access papers (continued):
Sharing a sentence is not in itself a finding about the gene and the disease.
atherosclerosis (55 papers, 2011 to 2025). A disease characterized by the build-up of fatty material and calcium deposition in the arterial wall resulting in partial or complete occlusion of the arterial lumen. "Lipocalin-2 (LCN-2): LCN2 is a member of the lipocalin family, linked to inflammation and atherosclerosis." (PMID 40001586, 2025). "In the case of atherosclerosis, numerous studies have reported that increased levels of serum LCN-2 correlate with atherosclerosis risk factors, disease severity burden, and mortality." (PMID 39330316, 2024). "Several studies suggest that LCN2 protein is a risk factor for atherosclerosis and myocardial ischemic injury." (PMID 38402404, 2024). "It has been reported that high levels of lipocalin-2 are associated with markers of atherosclerosis, presence and severity of CAD." (PMID 34660715, 2021). "Lcn2 expression is closely related to metabolism and inflammation, both of which contribute to the pathogenic process of atherosclerosis." (PMID 24359145, 2013). "Elevated serum or urinary LCN2 levels are associated with atherosclerosis risk factors, disease severity and mortality, with studies suggesting that LCN2 could serve as a prognostic marker with patients presenting with acute coronary syndromes." (PMID 41303567, 2025). "There is an increase in circulating lipocalin-2 in patients with atherosclerosis and coronary artery disease and coronary CVD." (PMID 37240282, 2023). "For example, it has been confirmed that lipocalin-2, a proinflammatory protein, promotes atherosclerosis by enhancing M1-type macrophage polarization, foam-cell formation, and inflammatory activation of endothelial cells." (PMID 36158875, 2022). "For instance, some proteins related to atherosclerosis were down-regulated in SF, such as ARG2, CD14, CD44, engulfment, and cell motility protein 1 (ELMO1), neutrophil gelatinase-associated lipocalin (LCN2), MPO, S100A8, or S100A9." (PMID 34572333, 2021). "LCN2, which is also expressed in macrophages within atherosclerosis lesions, is involved in atherogenesis by advancing polarization and migration of monocytic cells and development of foam cells." (PMID 32157804, 2020). "In particular, LCN2 plays a crucial role in vascular remodeling and plaque instability in atherosclerosis." (PMID 33192583, 2020). "In regard to diabetic complications such as atherosclerosis, recent evidence suggests that LCN2 plays a pivotal role in vascular remodeling and plaque instability specifically LCN2 expressed in macrophages." (PMID 28709459, 2017). "In regard to atherosclerosis, recent evidence suggests that LCN2 plays a crucial role in vascular remodeling and plaque instability." (PMID 26367277, 2015). "Our findings were further correlated with LCN2 plasma levels in atherosclerosis-prone mice as well as in patients with different degrees of CAD severity." (PMID 26367277, 2015). "Studies in animal models have shown that murine atherosclerosis is accompanied by increased levels of serum LCN2 and that conditions of hypoxia and myocardial infarction (MI) induce Lcn2 mRNA expression." (PMID 24359145, 2013). "In this study, we evaluated the association of serum lipocalin-2 and RBP4 with intima-media thickness (IMT) and subclinical atherosclerosis in type 2 diabetic patients." (PMID 23799122, 2013). "Studies to elucidate the pathogenic molecular mechanism of Lcn2 in atherosclerosis and CAD have shown that the Lcn2/MMP-9 complex acts to destabilize the artery plaque." (PMID 24359145, 2013). "Molecular studies reported that lipocalin-2 may contribute to the development of atherosclerosis by inducing inflammation." (PMID 40951890, 2025). "Lipocalin-2 deficiency promotes the growth of the lesion in the early stages of the disease, while it reduces the activity of MMP-9 and the size of the necrotic nucleus in progressive atherosclerosis." (PMID 37240282, 2023).
atherosclerosis (continued). "There is also evidence to suggest that lipocalin-2 may play a role in vascular remodeling and plaque instability in atherosclerosis." (PMID 34660715, 2021). "To study the local role of adipo/cytokines in atherosclerosis, we evaluated the presence of adiponectin, visfatin, lipocalin-2, resistin, IL-6 and TNFR2 in secretomes of the unstable carotid atherosclerotic plaque and non-atherosclerotic mammary artery tissue cultures." (PMID 27391230, 2016). "Moreover, recent evidence suggests that LCN2 plays a crucial role in vascular remodelling and plaque instability in atherosclerosis." (PMID 26367277, 2015). "Our study revealed an independent correlation between subclinical atherosclerosis and serum lipocalin-2 and RBP4 levels in type 2 diabetic patients, suggesting that these lipocalins might be involved in the early stage of diabetic vascular complications." (PMID 23799122, 2013). "The significant association between lipocalin-2 or RBP4 and subclinical atherosclerosis remained unchanged after the HOMA-IR was taken into consideration when performing regression (OR 2.18, 95% CI 1.08–4.38, P = 0.029; OR 1.17, 95% CI 1.11–1.24, P<0.001, respectively)." (PMID 23799122, 2013). "More importantly, there are evidences suggesting that lipocalin-2 may participate in the development of atherosclerosis by inducing inflammation." (PMID 23799122, 2013). "Similar results were obtained in the current study of Chinese cohort, suggesting that LCN2 might prompt the inflammatory process that induces atherosclerosis." (PMID 24359145, 2013). "Further studies are needed to investigate the role of LCN2 in atherosclerosis in detail." (PMID 21573245, 2011). "In addition, Lcn2 expression has been detected in clinical specimens of atherosclerosis plaques (particularly in the vascular endothelial cell, smooth muscle cell and macrophage components) and damaged myocardium, as well as in vitro analysis of arterial plaques." (PMID 24359145, 2013). "LCN2 has been reported to regulate the enzymatic activity of MMP-9, acting as a key mediator of plaque instability in atherosclerosis." (PMID 33192583, 2020). "Adipokines released by PVAT include adiponectin, leptin, resistin, visfatin, chemerin, lipocalin-2 (LCN2), fatty acid binding protein (FABP), which show direct evidence of PVAT-derived adipokines have effects on the progression of atherosclerosis." (PMID 30305178, 2018). "Three newly discovered adipokines: visfatin, LCN-2, FABP represent a further link between adipose tissue and atherosclerosis due to their ability to activate macrophages and regulate their phenotypes." (PMID 30305178, 2018). "In both atherosclerotic plaques and the intima of injured vessels, lipocalin-2 colocalizes with matrix metalloproteinase 9 (MMP-9), a key protease in inflammation and atherosclerosis." (PMID 23799122, 2013). "However, the regulatory roles of circulating lipocalin-2 and RBP4 in type 2 diabetic patients with or without subclinical atherosclerosis have not been reported yet." (PMID 23799122, 2013).
ischemia (55 papers, 2008 to 2025). A hypoperfusion of the BLOOD through an organ or tissue caused by a PATHOLOGIC CONSTRICTION or obstruction of its BLOOD VESSELS, or an absence of BLOOD CIRCULATION. "In vitro ischemia in astrocyte cultures triggered a significant increase of secreted LCN2 in astrocytic exosomes, which caused neuronal cell death and neurodegeneration." (PMID 35440572, 2022). "Our findings suggested the involvement of proteins associated with thrombus formation (such as D-dimer and ADAMTS13), proteins associated with acute phase of ischemia (such as lipocalin-2, IP-10 and SAA), and angiogenic markers such as platelet derived growth factor (PDGF)-AA)." (PMID 33930055, 2021). "Administration of Lcn2 antibody at 4 h after ischemia significantly reduced neurological deficits, cerebral infarction, edema, blood brain barrier leakage, and infiltration of neutrophils." (PMID 38180614, 2024). "For example, ischemia‐induced astrocytic exosomal secretion of LCN2 promotes neuronal cell death and neurodegeneration in vitro." (PMID 38888462, 2024). "Plasma levels of Lcn2 measured in patients 1 week after ischemia contribute to the prediction of clinical outcome at 90 days and reflect the systemic response to post-ischemia infections." (PMID 38180614, 2024). "During the past few years, LCN2 was considered an attractive blood‐based biomarker of inflammation and ischemia." (PMID 36974345, 2023). "Immunoblot analysis revealed that in vitro ischemia moderately stimulated LCN2 protein expression in OGD/R ACM (p = 0.23)." (PMID 35440572, 2022). "Lipocalin 2 (Lcn2) is an important marker of renal injury and its production markedly increases in response to stimulation such as ischemia." (PMID 36364144, 2022). "To further elucidate the role of NHE1 in astrocyte-derived LCN2 protein in neurodegeneration after in vitro ischemia, we harvested ACM after in vitro ischemia from primary astrocyte cultures in the presence or absence of HOE642." (PMID 35440572, 2022). "Inhibition of NHE1 activity during in vitro ischemia with its potent inhibitor HOE642 significantly reduced astrocytic LCN2+ exosome secretion." (PMID 35440572, 2022). "Our results showed that the increase of Kim1 and Lcn2 expression emerged at 16 min and 22 min of ischemia respectively, and gradually enhanced according to the ischemia time." (PMID 36465563, 2022). "Several reports revealed a detrimental role of LCN2, including impairing synaptic plasticity, promoting neuron death, or acting in a pro-inflammatory manner during ischemia and Alzheimer’s disease, and polarizing microglia toward pro-inflammatory phenotype." (PMID 35413913, 2022). "Lcn2 is expressed in kidney cells and its production markedly increases in response to stimulation such as ischemia, and plays a critical role in renal ischemia/reperfusion induced AKI by regulating autophagy activation." (PMID 36465563, 2022). "In our study, we detected increase in LCN2+ exosome secretion by astrocytes subjected to in vitro ischemia." (PMID 35440572, 2022). "Lipocalin-2 also shows increased level in various human diseases such as inflammation, infection, and ischemia." (PMID 32153594, 2020). "This study probed the presence and effects of functional polarization of astrocytes after cerebral ischemia and demonstrated that LCN2 played an essential role in classical activation of astrocytes and aggravated the ischemia-induced brain damage." (PMID 31426811, 2019). "Future studies have to address the additional LCN2 sources after ischemia and their role in the complex brain–body interaction." (PMID 30871254, 2019). "These chemokines appear to be under the control of LCN2-signaling and are increased in the chronic stage of ischemia." (PMID 30871254, 2019). "LCN2 is an acute-phase protein demonstrating increased systemic levels in many human diseases, especially inflammation, infection, and ischemia." (PMID 31269059, 2019).
ischemia (continued). "In this study, a novel signaling pathway involving LCN2 for the EGB-mediated dysfunction of reactive astrocyte properties in ischemia was reported." (PMID 29867513, 2018). "Upregulation of the gene expression of the tubular injury marker Lcn2 (NGAL) shows an ischemia time-dependent effect, with significantly reduced upregulation after 18 and 21 minutes of UIRI as compared to 30 minutes at week 6 (p<0.05)." (PMID 27007127, 2016). "A greater decrease of MMP9 and LCN2 gene expression was seen in the IBT group during total ischemia (p = 0.003 and p = 0.018)." (PMID 27808277, 2016). "Lcn2 and serpina3n have been shown as markers of the early phase of reactive astrogliosis in both ischemia and neuroinflammation injury models." (PMID 23951329, 2013). "To further investigate whether increased NOX4 activity is driving LCN2 expression in astrocytes, we tested the effect of NOX4 specific inhibitor GKT137831 on the expression of LCN2 protein in astrocytes subjected to in vitro ischemia." (PMID 35440572, 2022). "To test this, we first investigated the changes of LCN2 protein expression and secretion in astrocytes using a well-established in vitro ischemia model (3 h oxygen/glucose deprivation (OGD)/ 24 h reoxygenation (OGD/R)) with or without the NHE1 inhibitor HOE642." (PMID 35440572, 2022). "Therefore, Lcn2 is likely to have value as a biomarker in ischemia patients." (PMID 38180614, 2024). "Compared to the sham-operated animals, renal ischemia of various durations increased all renal injury markers (BUN and Lcn-2 concentrations, Lcn-2 renal gene expression and ATN score) in proportion to the severity of ischemia." (PMID 38474193, 2024). "Lipocalin 2, also known as NGAL, is a crucial injury-response factor that showed elevated expression levels in single-cell RNA-seq in an ischemia–reperfusion mouse model of AKI." (PMID 36230932, 2022). "Many of them have been previously correlated with response to ischemia (MAP 4, HPX, S100A proteins) as well as with angiogenic- and revascularization-related processes (LCN2, LRG1, CD44, MAPKAPK2)." (PMID 32143690, 2020). "It has been reported that Lcn2 is expressed in the ischemic brain after temporary experimental ischemia and accompanied by the accumulation of cellular nonheme iron." (PMID 38180614, 2024). "Interestingly, clusterin, lipocalin 2, litaf, and TNFR1a are also upregulated by other injuries as elevation of intraocular pressure (IOP) or ischemia." (PMID 18552980, 2008).
colorectal cancer (53 papers, 2012 to 2025). A primary or metastatic malignant neoplasm that affects the colon or rectum. "Multivariable‐adjusted hazard ratios (HRs)a and 95% confidence intervals (95% CIs) for the association of LCN2 with colorectal cancer and its subsites, stratified by waist circumference categories." (PMID 39511728, 2025). "Incidence rate ratios (IRRs)a and 95% confidence intervals (CIs) for the association of LCN2 with colorectal cancer and subsites, overall and by sex." (PMID 39511728, 2025). "The LCN2 level was positively associated with colorectal cancer stage and recurrence of stage II tumors, and LCN2 expression is an independent prognostic factor for overall survival." (PMID 40109857, 2025). "We, therefore, explored the association of pre‐diagnostic circulating LCN2 concentrations with incident colorectal cancer (CRC) in a nested case–control study within the in the European Prospective Investigation into Cancer and Nutrition (EPIC) cohort." (PMID 39511728, 2025). "Some studies reported high expression level of LCN2 in some cancer types, such as breast cancer and colorectal cancer, and its expression level was associated with cancer progression, poorer prognosis and decreased overall survival." (PMID 38035773, 2024). "In colorectal cancer cell lines LCN2 overexpression was linked to increased invasion of cells and loss of cell-to-cell adhesion." (PMID 39839775, 2024). "The results of their study revealed the role of LCN2 major molecular mechanisms in the progression of colorectal cancer, indicating LCN2 as a possible diagnostic marker and a therapeutic target in colorectal cancer." (PMID 31151292, 2019). "Both functions of LCN2 are required to promote invasion, and LCN2 expression is associated with increased tumor stage in colorectal cancer and present in 60–70% of colorectal cancers." (PMID 40356520, 2025). "LCN2 appeared to be the 2nd most significant protein and played an important role in the enzymatic activity of matrix metalloprotease-9 causing metastasis of colorectal cancer cells It has a physical association with several other transcription factors and other protein classes." (PMID 39839775, 2024). "In colorectal cancer, metastatic cells exhibit reduced LCN2 expression, and LCN2 knockdown enhances glucose uptake and lactate production while downregulating energy metabolism genes." (PMID 41303420, 2025). "In colorectal cancer, LCN2 manipulates EMT by suppressing snail, another key transcription factor involved in EMT." (PMID 40109857, 2025). "Included within the upregulated genes in the concurrent mutation group were some previously linked with colorectal cancer carcinogenesis, including NFKBIZ, CCL20, LCN2, PLOD2, MUC1, and MUC4." (PMID 40757636, 2025). "Conversely, the suspected dysplasia was characterized by the expression of CXCL2/3 (inflammatory markers), LCN2 (a secretory protein potentially acting as a tumor suppressor in colorectal cancer), and SOD2 and NCOA7 (stress response genes)." (PMID 40667282, 2025). "The tumor-suppressing role of LCN2 was further supported by an independent study that showed that the invasion and migration of colorectal cancer cells were suppressed by LCN2." (PMID 40109857, 2025). "His group demonstrated that lipocalin 2 (LCN2) is a potential therapeutic target in colorectal cancers." (PMID 39140283, 2024). "Seven proteins, TFF3, LCN2, CEACAM5, TFF1, SELE, RETN, and AHCY were found to be upregulated in other databases and also in our UK Biobank where TFF3 and LCN2 were found to be the most significant proteins and were highly expressed in colorectal cancer." (PMID 39839775, 2024). "Lcn-2 levels in patients with colorectal cancer were significantly higher compared with those in healthy individuals (controls: 7.8 ± 1.0 vs. colorectal cancer: 16.3 3.4 ng/mg feces, P < 0.036)." (PMID 38934090, 2024).